SNAI1 (snail family transcriptional repressor 1)
Diseases named in the same sentence as SNAI1 in open-access papers (continued):
Sharing a sentence is not in itself a finding about the gene and the disease.
tumor (continued). "CYD19 impairs EMT-associated tumor invasion and metastasis by reversing SNAI1-driven EMT; this finding provides evidence that pharmacologic interference with SNAI1 acetylation may exert potent therapeutic effects in patients with cancer." (PMID 34681726, 2021). "In addition, the study suggested that SMAD7 and SNAI1 hypomethylation is associated with tumor recurrence." (PMID 34571856, 2021). "Moreover, SNAI1 expression was associated with tumor-infiltrating immune cells in gastrointestinal cancers." (PMID 32833672, 2020). "In conclusion, our work shows that ZNF750, a novel significantly mutated gene in ESCC, may act as a tumor suppressor via directly regulating SNAI1 expression and inhibit the EMT process of ESCC cells." (PMID 32042337, 2020). "High levels of SNAI1 in cancer are associated with downregulation of E-cadherin expression, consequent activation of the Wnt/β-catenin pathway, and the acquisition of an aggressive tumor phenotype." (PMID 32244885, 2020). "Also signals for SNAI1 (encoding the transcription factor Snail), which controls tumor growth and stemness and is considered as typical EMT marker, were augmented in MSTO-CR cells." (PMID 30555628, 2018). "For instance, we reported that the induction of EMT in a colorectal cancer cell line, by the forced expression of the master regulator of the EMT process Snail family transcriptional repressor 1 (SNAI1; best known as Snail), is associated with the increased immunogenicity of tumor cells in vitro." (PMID 30597841, 2018). "Although the presence of a SNAI1-positive tumor component of >10% area was associated with a poorer prognosis in our cohort, the significance of occasional SNAI1-positive cells for patient outcome remains unclear." (PMID 20181105, 2010). "Next, SNAI1 expression in tumor-associated stroma was examined with regard to outcome parameters." (PMID 20181105, 2010). "Although SNAI1 expression is an infrequent event, its presence in a significant proportion of tumor cells may be associated with a poor prognosis and can herald the presence of a sarcomatoid component." (PMID 20181105, 2010). "Besides ER, bone metastases are frequently associated with tumor SNAI1 expression." (PMID 21914172, 2011). "Our results suggest that EMT-TFs, particularly the interplay between SNAI1 and ZEB1 is associated with tumor progression, metastasis, and poor survival." (PMID 41481650, 2026). "We found a strong correlation between SNAI1 expression and increased peripancreatic invasion, highlighting SNAI1’s pivotal role in enhancing tumor aggressiveness." (PMID 41481650, 2026). "YY1 also acts as a pleiotropic factor interacting with various factors in the transcription initiation complex of tumor‐related genes, including SNAI1." (PMID 40145793, 2025). "The EMT is considered a cellular process to induce cell stemness, which causes tumor metastasis and treatment resistance, for instance, ZEB1, SNAI1, and TWIST1." (PMID 39827156, 2025). "Recent studies confirmed that SNAI1 has been extensively characterized as a key driver of tumor aggressiveness and metastasis through contributing to the EMT program." (PMID 40234378, 2025). "During EMT, the zinc finger family of transcription factors, including SNAI1, Slug, Twist, and matrix metalloproteinases (MMPs), are upregulated, which correlates with enhanced tumor cell invasion and motility." (PMID 40429774, 2025). "They found that enhancing autophagy accelerates the degradation of the core protein snail family transcriptional repressor 1 (SNAI1), thereby inhibiting tumor epithelial–mesenchymal transition and metastasis." (PMID 40006565, 2025). "Given the crucial role of M0 macrophages and mast cells in the tumour microenvironment, the associations between CSNK2A1,SNAI1,and these immune cells deserve further investigation." (PMID 40028162, 2025). "Snai1 overexpression partially rescued the GC tumor cellular phenotypes, including proliferation, colony formation, cell migration, and invasion." (PMID 39998882, 2025).
tumor (continued). "Snai1 (snail family transcriptional repressor 1) is a zinc finger transcription factor that regulates tumor growth and metastasis." (PMID 39796281, 2025). "Despite limited research, SNAI1’s critical role in other tumours has been confirmed, highlighting the need for further exploration." (PMID 40028162, 2025). "SNAI1 is an EMT regulator that promotes tumour invasiveness by repressing CDH1/E-cadherin transcription." (PMID 40642068, 2025). "Remarkably, the protein expression of VRK1 also exhibited a positive correlation with SNAI1 expression in mice tumor tissues." (PMID 40234378, 2025). "SNAI1 is also closely related to the stemness and migration of tumor cells, and the overexpression of SNAI1 can significantly increase the malignant biological manifestations of tumors." (PMID 40295497, 2025). "In CRC, intestinal epithelial SNAI1 facilitates tumor development through EMT and the Wnt/β-catenin signaling pathway." (PMID 40613523, 2025). "This decision was guided by the fact that the analysis of human expression data provided more comprehensive evidence for the upregulation of Snai1 in the tumor endothelium than for Slug and Twist1." (PMID 39095583, 2024). "In contrast to Twist1 OE, OE of Snai1 in the tumor cells increased the relative and absolute volume of CD31+ PVs in the VTSs." (PMID 38678014, 2024). "Subsequently, TET cells were inoculated into the left ventricle of 5- to 6-week-old BALB/c nude mice, and we found that the overexpression of SNAI1 significantly induced tumor metastasis in vivo." (PMID 39702326, 2024). "Immunohistochemical analysis of 528 CRC tumors demonstrated that not only SNAI1, but also A1AT protein expression levels were associated with tumor stage, lymph node metastasis and poor clinical outcome." (PMID 38066386, 2024). "Inhibition of Snai1 expression led to a mature, better stabilized, less permeable, and denser tumor vasculature in mouse models." (PMID 39095583, 2024). "In fact, GPx2 KD tumours showed HIF1α upregulation that was accompanied by increased SNAI1, TWIST, N-CAD and decreased E-CAD expression, thus supporting effects of HIF1α on EMT." (PMID 38238426, 2024). "In murine models, even partial reduction of endothelial Snai1-signaling improved tumor vessel architecture, maturity, and patency." (PMID 39095583, 2024). "We showed that the initiation of EMT by INHBA is mediated by the upregulation of SNAI2 and SNAI1, rendering tumor cells more migratory." (PMID 38329386, 2024). "USP3 mediates the deubiquitination of snail family transcriptional repressor 1 (SNAIL1) by activating tumor development and cell transformation." (PMID 38667297, 2024). "In vitro, experiments demonstrated that Snai1 (similarly Slug and Twist1) regulates endothelial permeability, permissiveness for tumor cell transmigration, and tip/stalk cell formation." (PMID 39095583, 2024). "Because we were interested in studying Snai1 as a potential target for tumor vascular re-engineering in a therapeutic setting, we decided on generating mice heterozygous for Snai1 instead of a complete, homozygous knock-out." (PMID 39095583, 2024). "We analyzed gene expression data from the GEPIA2 website and five GEO cohorts, and the results further supported the previous conclusion (the SNAI1 gene expression level showed a trend of lower expression in tumor tissues in GSE3678 and GSE27155)." (PMID 38329430, 2024). "It was validated that SNAI1 facilitates tumor progression and metastasis through the PIK3R2/p-EphA2 axis." (PMID 39702326, 2024). "The expression of KRT7 correlates with the tumor growth and metastasis and the levels of the EMT-associated transcription factors (SNAI1, SNAI2, TWIST1, TWIST2), and the mesenchymal markers, such as fibronectin, and vimentin (VIM)." (PMID 39329988, 2024). "To further assess the impact of SNAI1 expression in primary TET cells on the tumor microenvironment, we subsequently conducted scRNA-seq analysis of the PDX models." (PMID 39702326, 2024).
tumor (continued). "Endothelial Snai1 inhibition improved the tumor vasculature, with respect to all three parameters—a stark contrast to anti-VEGFA therapy that only improves vessel maturation but often reduces the already critical vessel density even further." (PMID 39095583, 2024). "The high expression of PD-L1 in tumor cells promotes lymph node metastasis and enhances glucose metabolism in tumor cells through the SNAI1/SIRT3 pathway, but PD-L1 has the opposite effect on T-cell glycolysis." (PMID 37342333, 2023). "SNAI1 induces EMT by binding to the epithelial-tumor suppressing gene CDH1, amongst other epithelial genes, repressing E-cadherin and claudins." (PMID 36980876, 2023). "BMP signaling exerts its tumor suppressive function in GBM through the upregulation of SNAI1 (also called SNAIL) and DLX2." (PMID 38049682, 2023). "The HRI signature consists of 11 HRDEGs, and we focused on the 5 key genes (RGS16, SNAI1, CDR2L, FRMD5, and FSTL3), which exhibited elevated expression levels in tumor tissues and are prognostic risk factors for CC." (PMID 36925652, 2023). "Inhibiting SNAI1 expression using knockdown techniques impedes tumor growth and metastasis by augmenting the number of tumor-infiltrating lymphocytes and systemic immune responses." (PMID 37444447, 2023). "The knockdown of these lncRNAs (oncogenic) downregulated the expression of ZEB1, Twist, Notch, and Slug/Snai1 and vice versa in overexpression studies for the tumour-suppressive lncRNAs." (PMID 37372103, 2023). "A previous study showed that SNAI1 expression is regulated by the secretion of MMP9 to induce EMT during tumor cell invasion." (PMID 37190063, 2023). "Accordingly, Snai1 gene elimination in adult mice retards tumor development and prevents metastasis." (PMID 37199012, 2023). "In pan-cancer studies, high expression of SNAI1 is mainly involved in the enhancement of stemness and migration of tumor cells, which significantly increases the malignant biological manifestation of tumors." (PMID 38033866, 2023). "Conversely, a growth reduction and differentiation were observed when the tumor was silenced for SNAI1." (PMID 36831458, 2023). "Tumours derived from GATM-knockdown cells expressed lower levels of Snai1, Cdh2 and Rhoa than tumours-derived from controls." (PMID 37370109, 2023). "In the mouse mammary tumor virus‐polyoma middle tumor‐antigen (MMTV‐PyMT) model of murine mammary gland tumors, Snai1 gene deletion, besides increasing tumor‐free lifespan, altered macrophage differentiation, with fewer expressing low levels of MHC class II." (PMID 37199012, 2023). "In vivo data confirm the suppressive roles of GATA6-AS1/SNAI1 in tumor growth and lung metastasis of PDAC." (PMID 38057853, 2023). "The PD-L1-integrin axis also increases the glucose metabolism and tumor cell proliferation through SNAI1-mediated downregulation of SIRT3 in CC, suggesting that the reprograming of Warburg effect is essential for the tumor cell dissemination." (PMID 36905477, 2023). "SNAI1 is regarded as a prognostic biomarker for GC, and its high expression is closely related to the poor overall survival of the tumor." (PMID 37017587, 2023). "TWIST, Snai1, and Slug are transcription factors that were found to endure in tumor cells with stem cell characteristics and play a crucial role in EMT events." (PMID 37375218, 2023). "As we and others have previously reported regarding tumor burden, depletion of Snai1 in 6‐week‐old MMTV‐PyMT mice increased their tumor‐free life with respect to mice with WT Snai1." (PMID 37199012, 2023). "Inhibition of HMGA2 blocks SNAIL1 (SNAI1) transcription and other mechanisms involved in tumour cell invasion and metastasis." (PMID 35203304, 2022). "Overexpression of other EMT-TFs such as ZEB2, TWIST1, and SNAI1 similarly reduced tumor growth and metastatic load arguing that different EMP states induced by distinct means in MCF-7 cells neither favor tumor progression nor metastasis." (PMID 36008376, 2022).
tumor (continued). "Our previous studies have shown that Salmonella can downregulate Matrix Metalloproteinases-9, C-X-C chemokine receptor type 4, heparinase and SNAI1 expression to reduce tumor metastasis." (PMID 36118522, 2022). "SNAI1 methylation levels among different immune cell types and tumor types are visualized in heatmaps." (PMID 35898399, 2022). "Upregulation of EMT transcription factors, such as TWIST1, ZEB1/2 and SNAI1/2 have been reported to promote migration and invasion of tumor cells in many types of tumors." (PMID 35205125, 2022). "Silencing of SNAI1 in MDA-MB-231 cells revealed loss of invasiveness in vitro, accompanied by reduced tumor growth and metastatic potential in xenografted mice." (PMID 36171192, 2022). "For example, disulfiram inhibits cell migration, invasion, and growth of tumor grafts through the ERK/NF-κB/SNAI1 signaling pathway." (PMID 34681726, 2021). "One of the major EMT-ATFs is SNAI1 that plays a key role in promoting chemoresistance, metastasis, and tumor progression." (PMID 33674749, 2021). "The lowest level of SNAI1/2 was observed in grade I tumors, and the level gradually increased with tumor grade up to grade IV." (PMID 34657130, 2021). "Tumor-intrinsic SNAI1 not only has direct effects on cell migration and invasion but also impacts the tumor microenvironment by altering tumor secretomes, thereby increasing the tendency of tumors to facilitate metastatic processes." (PMID 34207850, 2021). "During tumor metastasis, SNAI1 recruits epigenetic regulators to the CDH1 promoter, thus repressing its expression." (PMID 34681726, 2021). "Understanding how signaling networks integrate with SNAI1 in cancer progression will shed new light on the mechanism of tumor metastasis and help develop novel therapeutic strategies against cancer metastasis." (PMID 34681726, 2021). "Further study by the same group revealed that GLI1 regulates the expression of EMT-inducing transcription factors, TWIST1 and SNAI1, to promote tumor-initiating cell-like properties and consequently chemoresistance in the resistant sublines." (PMID 34638233, 2021). "More interestingly, it appears that miR-199a-5p overexpression in xenografts suppresses the tumour growth of PTC by downregulating SNAI1." (PMID 34073413, 2021). "Studies by us and others demonstrated that SNAI1 expression correlates with tumor grade and predicts a poor patient outcome 10-13." (PMID 34335956, 2021). "This complex binds to SNAI1 and prevents any interaction with DNA, thus reducing the invasive potential of tumor cells." (PMID 34681726, 2021). "A previous study identified a relationship between the expression of mesenchymal genes in tumor cells (e.g., SNAI1, TWIST1, and ZEB1) and the extent of clearance." (PMID 34396026, 2021). "Evidently, TWIST1 and SNAI1 levels were markedly elevated in these multidrug-resistant sublines exhibiting heightened tumor-initiating potential." (PMID 34638233, 2021). "Higher levels of expression of mesenchymal-associated genes SNAI1, SERPINE1, MSN, NRP1 and LAMC2 were observed in CTCs compared to primary tumour in three of the four models (the exception being LuCaP96)." (PMID 34206049, 2021). "Mesoporous silica nanoparticle-delivered RNAi effectively knocks down SNAI1 in vivo, resulting in reduced tumor burden, in support of its clinical use." (PMID 33806868, 2021). "In summary, our study unveils a mechanism by which STK39 promotes EMT and the metastasis of tumor cells by enhancing the stability of SNAI1." (PMID 34335956, 2021). "Cancer cells with a terminal mesenchymal phenotype characterized by high ZEB1, ZEB2 and SNAI1, exhibited impaired tumor-initiating capacity." (PMID 34063254, 2021). "In vivo, nanoparticle-delivered siRNA successfully knocked down SNAI1 in orthotopic patient-derived xenografts, accompanied by reduced stemness and increased let-7 expression, and reduced tumor burden." (PMID 33806868, 2021).
tumor (continued). "On the other side, Axin2, a canonical Wnt suppressor, acts as a potent tumor promoter by up-regulating the activity of SNAI1." (PMID 34768901, 2021). "In mice, we used nanoparticles to deliver small RNAs (RNAi) targeting SNAI1, resulting in restoration of let-7 levels, inhibition of stemness, and reduced tumor burden." (PMID 33806868, 2021). "Conversely, dual pharmacologic targeting of TGF-β and AURKA pathways efficiently reverses chemoresistance and impairs tumor progression through SNAI1 down-regulation, inhibition of cancer cell plasticity, and selective targeting of ALDH1high cells." (PMID 33674749, 2021). "That is, PD-L1 promotes tumor growth and metastasis via ITGB4/SNAI1/SIRT3 signaling, and this is one of the main causes of PD-L1 resistance." (PMID 32000802, 2020). "TOX3 has been newly identified as a ccRCC suppressor gene as it inhibited tumor cell migration and invasion by repressing the SNAIL members SNAI1 and SNAI2 at the transcriptional level." (PMID 32789468, 2020). "RMS is a tumor that originates from an impaired myogenic differentiation and SNAI1 has been suggested previously as a crucial regulator of myogenic differentiation." (PMID 32354171, 2020). "Pit1 is also known to upregulate Snai1, leading to tumor epithelial-mesenchymal transition (EMT) and their growth and metastasis." (PMID 32620903, 2020). "The downregulation of SNAI1 by shRNA results in the arrest of tumor growth in vivo, suggesting that SNAI1 is a crucial factor in ARMS growth." (PMID 32354171, 2020). "This revealed a significant positive correlation between STAMBPL1 and SNAI1 in both tumour types, with a p value <0.0001." (PMID 32636467, 2020). "It was shown that tumor cells expressing high levels of the EMT master transcription factor SNAI1 display enhanced tumor-initiating capacity and metastatic potential in mouse and human models." (PMID 33291403, 2020). "Taken together, our study elucidates an important role of EMT inducer Snai1 in regulating tumor neoangiogenesis, suggesting a potential therapeutic target for overcoming tumor EMT." (PMID 30975732, 2019). "(E) The protein level of N-cad, Snai1, β-catenin and Vimentin in ECs treated with Exo-3B or Exo-3B-KD from tumor cells." (PMID 31477130, 2019). "In HNSCC tissue samples, we found Twist and SNAI1 expression (EMT markers) to be related to NOVA1 status in tumor cells, as well as stromal spindle cells and T lymphocytes." (PMID 31375778, 2019). "SNAI1/SLUG expression (another marker of EMT) in tumor cells was related to NOVA1 expression status in T lymphocytes and stromal spindle cells/fibroblasts, but not to NOVA1 status in tumor cells." (PMID 31375778, 2019). "Chromatin immunoprecipitation assays in cisplatin-resistant atypical teratoid/rhabdoid tumor cells indicated that STAT3 also binds to the SNAI1 promoter, although in a more distant region than NFκB." (PMID 31141910, 2019). "The xenograft tumor section analysis confirmed reduced SNAI1 expression in samples from miR-30a injected nude mice." (PMID 30770779, 2019). "In the present study, we investigated promoter methylation in six genes associated with tumour invasivity (ADAM23, uPA, CXCL12, TWIST1, SNAI1 and SNAI2)." (PMID 30189837, 2018). "SNAI1 can induce tumorigenesis, promote invasion and migration, facilitate tumor development and impair sensitivity to chemotherapeutic drugs, and high SNAI1 expression was shown to be correlated with poor outcomes in diverse tumor types." (PMID 30419922, 2018). "DT also suppressed the expression of tumor epithelial–mesenchymal transition genes, including RhoA and SNAI1." (PMID 28157698, 2017). "Among them, the importance of SNAI1 expression perturbation in the tumor stroma has been put forward in numerous studies." (PMID 29041931, 2017). "Together, these data support roles for ICN1 and SNAI1 in regulating continued tumor growth and maintenance in vivo." (PMID 28614716, 2017).